TIGAR (TP53 induced glycolysis regulatory phosphatase)
Diseases named in the same sentence as TIGAR in open-access papers (continued):
Sharing a sentence is not in itself a finding about the gene and the disease.
ischemia (2 papers, 2016 to 2019). A hypoperfusion of the BLOOD through an organ or tissue caused by a PATHOLOGIC CONSTRICTION or obstruction of its BLOOD VESSELS, or an absence of BLOOD CIRCULATION. "Preconditioning promoted PPP flux, as evidenced by increased NADPH and GSH, which helped to reduce ROS formation and neuronal apoptosis during subsequent ischemia, while TIGAR knockdown cancelled these effects." (PMID 27256465, 2016).
liver cancer (2 papers, 2015 to 2020). An epithelial or non-epithelial malignant neoplasm that arises from the liver. "Moreover, other transcription factors such as SP1 and CREB14, 15 have been shown to have a role in regulating the basal expression of TIGAR in liver cancer cell lines." (PMID 26247727, 2015).
lung adenocarcinoma (2 papers, 2013 to 2019). A carcinoma that arises from the lung and is characterized by the presence of malignant glandular epithelial cells. "We demonstrated that TIGAR expression was significantly higher in lung adenocarcinoma tissue than in squamous carcinoma (P<0.01), which is consistent with observations of lower SUV in lung adenocarcinoma." (PMID 24363807, 2013).
lymphoma (2 papers, 2021 to 2023). A malignant (clonal) proliferation of B- lymphocytes or T- lymphocytes which involves the lymph nodes, bone marrow and/or extranodal sites.
myocardial infarction (2 papers, 2022 to 2026). Gross necrosis of the myocardium, as a result of interruption of the blood supply to the area, as in coronary thrombosis. "For example, in the brain TIGAR expression was reported to protect against ischemic/reperfusion injury, whereas in the heart TIGAR deficiency protected myocardial infarction and in pressure-overloaded hearts." (PMID 35254259, 2022).
Parkinson disease (2 papers, 2022 to 2026). A progressive degenerative disorder of the central nervous system characterized by loss of dopamine producing neurons in the substantia nigra and the presence of Lewy bodies in the substantia nigra and locus coeruleus. "Because the oxidative damage of dopaminergic nigrostriatal neuronsis important in Parkinson’s disease (PD) pathogenesis, and TIGAR is significantly associated with neuronal glucose metabolism, PPP activity and oxidative stress, it may participate in the pathogenesis of PD." (PMID 36437984, 2022).
stomach adenocarcinoma (2 papers, 2019 to 2023). "The low SYK expression (p = 2.895 × 10−3), NDRG1_pT346 (p = 3.872 × 10−2), P90RSK (p = 1.991 × 10−3), and TIGAR (p = 2.885 × 10−4) and the high XBP1 expression (p = 8.621 × 10−4) were significantly positively associated with the poor overall survival of STAD (stomach adenocarcinoma) patients." (PMID 36979962, 2023).
T cell lymphoma (2 papers, 2019 to 2021). "In an in vivo xenograft model of human T-cell leukemia virus type-1 (HTLV-1)-induced T cell lymphoma, TIGAR was highly expressed." (PMID 34299056, 2021).
acute leukemia (1 paper, 2016). A clonal (malignant) hematopoietic disorder with an acute onset, affecting the bone marrow and the peripheral blood. "As TIGAR showed a high expression in primary AML cells and human acute leukemia cell lines, we next tested whether TIGAR knockdown may affect the proliferation of acute leukemia cells." (PMID 27884166, 2016). "TIGAR might be a novel target for treating human acute leukemia." (PMID 27884166, 2016). "Next, we tested whether glycolysis may induce TIGAR expression in human acute leukemia cells." (PMID 27884166, 2016). "However, the function of TIGAR in human chronic or acute leukemia remains unknown." (PMID 27884166, 2016). "We also overexpressed TIGAR in K562 cells (TIGAR low expressed acute leukemia cell line) and found that 2-DG but not CoCl2 induced the expression of TIGAR in K562 cells slightly." (PMID 27884166, 2016).
acute promyelocytic leukemia (1 paper, 2022). An aggressive form of acute myeloid leukemia (AML), characterized by arrest of leukocyte differentiation at the promyelocyte stage, due to a specific chromosomal translocation t(15;17) in myeloid cells.
atherosclerosis (1 paper, 2024). A disease characterized by the build-up of fatty material and calcium deposition in the arterial wall resulting in partial or complete occlusion of the arterial lumen. "Previous studies have reported that TIGAR increases during the formation of macrophage foam cells and atherosclerosis." (PMID 39091612, 2024).
brain tumors (1 paper, 2022). "Further studies are needed to elucidate the complex role and mechanism of TIGAR in the occurrence, development and treatment resistance of brain tumors." (PMID 36437984, 2022).
cataract (1 paper, 2025). Partial or complete opacity of the crystalline lens of one or both eyes that decreases visual acuity and eventually results in blindness. "The bioinformatics and RT-PCR results in this study showed that TIGAR significantly increased in the cataract group compared to that in the control group." (PMID 40598458, 2025). "TIGAR and IL6 were found to be causally linked to cataracts risk." (PMID 40598458, 2025). "We evaluated the causal link between TIGAR and IL6 levels and cataracts." (PMID 40598458, 2025). "TIGAR and IL6 were identified to be causally associated with cataracts." (PMID 40598458, 2025). "In summary, based on integrated bioinformatics analysis, in vitro experimental verification, and MR analysis, we determined two ferroptosis-specific expressed genes, TIGAR and IL6, as potential biomarkers for the diagnosis and treatment of cataracts." (PMID 40598458, 2025). "We specifically selected individuals from the European population in our dataset to eliminate any confounding factors between SNPs and TIGAR, IL6, and cataracts." (PMID 40598458, 2025).
Cognitive impairment (1 paper, 2019). Abnormal cognition is characterized by deficits in thinking, reasoning, or remembering. "Future clinical studies may identify TIGAR as a therapeutic target for the treatment of diabetic neuropathy and cognitive impairment." (PMID 31456661, 2019). "Importantly, overexpression of TIGAR in the hippocampus ameliorated STZ-induced cognitive impairment in mice." (PMID 31456661, 2019).
diabetic neuropathy (1 paper, 2019). A chronic, pathological complication associated with diabetes mellitus, where nerve damages are incurred due to diabetic microvascular injury involving small blood vessels that supply these nerves, resulting in peripheral and/or autonomic nerve dysfunction. "Fully understanding the mechanism of TIGAR in high glucose-induced neuronal injury may offer a new therapeutic approach in diabetic neuropathy." (PMID 31456661, 2019). "Therefore, our data demonstrated that TIGAR may have an anti-apoptosis effect via up-regulation of autophagy in diabetic neuropathy." (PMID 31456661, 2019).
epilepsy (1 paper, 2022). A brain disorder characterized by episodes of abnormally increased neuronal discharge resulting in transient episodes of sensory or motor neurological dysfunction, or psychic dysfunction. "Oxidative stress and oxidative stress-induced neuronal apoptosis may be related to the occurrence and development of epilepsy, and TIGAR has antioxidant effect." (PMID 36437984, 2022). "The increase of TIGAR expression is possibly a feedback mechanism to promote NADPH production and inhibit oxidative stress after epilepsy." (PMID 36437984, 2022).
Fanconi anemia (1 paper, 2019). Fanconi anemia (FA) is a hereditary DNA repair disorder characterized by progressive pancytopenia with bone marrow failure, variable congenital malformations and predisposition to develop hematological or solid tumors. "Accordingly, downregulation of BRCA1 and Fanconi anemia pathway in TIGAR-deficient cells may provide a molecular mechanism attributable to the increased sensitivity to olaparib after TIGAR KD in cancer cells." (PMID 31508509, 2019). "The annotation and enrichment analysis of genes downregulated by TIGAR KD indicates that the gene set is enriched for the Fanconi anemia pathway, DNA repair, DNA strand elongation, and cell cycle progression." (PMID 31508509, 2019). "TIGAR knockdown enhances sensitivity to olaparib in cancer cells via downregulation of BRCA1 and the Fanconi anemia pathway and increases senescence of these cells by affecting metabolic pathways and increasing the cytotoxic effects of olaparib." (PMID 31508509, 2019). "Consistent with both GSEA and the Metascape pathway analyses, we validated downregulation of genes involved in the Fanconi anemia pathway, such as BRCA2 and RAD51, after TIGAR KD with two different shRNAs." (PMID 31508509, 2019). "Secondly, TIGAR KD induces “BRCAness” by downregulation of BRCA1 and the Fanconi anemia pathway." (PMID 31508509, 2019).
fibrosis (1 paper, 2022). the formation of excess fibrous connective tissue in an organ or tissue in a reparative or reactive process. "Although our present study revealed that Ang II‐infusion in the WT mice appears to show only mild fibrosis and glomerular injury, knockout of TIGAR significantly sensitizes Ang‐II‐induced renal fibrosis and glomerular injury without altering blood pressure." (PMID 35441828, 2022).
gestational diabetes (1 paper, 2023). Carbohydrate intolerance first diagnosed during pregnancy.
glucose metabolism disorders (1 paper, 2025). "In addition, studies on epigenetic biological correlations related to inflammation, oxidative stress, and glucose metabolism disorders have found that the expression of NFKB1 and TIGAR genes is upregulated in visceral fat cells of obese patients with intermittent or chronic hyperglycemia." (PMID 40508108, 2025).
hypertrophic cardiomyopathy (1 paper, 2024). A condition in which the myocardium is hypertrophied without an obvious cause. "In contrast, focal adhesion, hypertrophic cardiomyopathy, hypertrophic cardiomyopathy extracellular matrix receptor interaction, drug metabolism cytochrome p450, and tyrosine metabolism were found to be negatively correlated with elevated TIGAR levels." (PMID 39091612, 2024).
Hypoglycemia (1 paper, 2019). A decreased concentration of glucose in the blood.
Insulin resistance (1 paper, 2022). Increased resistance towards insulin, that is, diminished effectiveness of insulin in reducing blood glucose levels.
intrahepatic cholangiocarcinoma (1 paper, 2025). A carcinoma that arises from the intrahepatic bile duct epithelium in any site of the intrahepatic biliary tree. "In addition, in a study of intrahepatic cholangiocarcinoma, TIGAR knockdown reduced cell motility (cell proliferation/migration/invasion/colony formation ability) and increased ROS and lipid peroxidation, suggesting that TIGAR knockdown induces ferroptosis." (PMID 40598458, 2025).
Myocardial fibrosis (1 paper, 2024). "Ang-II also induced myocardial fibrosis and impaired systolic and diastolic function, which were not affected by the ablation of TIGAR." (PMID 38397106, 2024).
neuroblastoma (1 paper, 2018). Neuroblastoma (NB) is the most common solid, extracranial childhood tumor. "Similarly, TIGAR expression was found decreased with a sonodynamic therapy tested in a neuroblastoma cell model which decreases cell proliferation, possibly through increased ROS levels." (PMID 30234009, 2018). "Thus, treatment of neuroblastoma cells with D-galactose induces necroptosis and autophagy, as reflected in the upregulation of BMF, BNIP3, ATG5, and TIGAR, without affecting the expression of the genes associated with apoptosis." (PMID 30234009, 2018).
osteoporosis (1 paper, 2026). A condition of reduced bone mass, with decreased cortical thickness and a decrease in the number and size of the trabeculae of cancellous bone (but normal chemical composition), resulting in increased fracture incidence. "Taken together, the current studies indicated that Dex damaged TIGAR expression in bone tissues and pre-osteoblasts, whereas restoration of TIGAR expression can alleviate Dex-induced osteoporosis in mice by improving osteogenic activity." (PMID 41487468, 2026). "The role of TIGAR in Dex-induced osteoporosis was clarified using TIGAR transgenic (TG) mice." (PMID 41487468, 2026). "Furthermore, we demonstrate that TIGAR overexpression improves Dex-induced osteoporosis by promoting osteogenic differentiation and activity in vitro and in vivo." (PMID 41487468, 2026).
osteosarcoma (1 paper, 2023). A usually aggressive malignant bone-forming mesenchymal neoplasm, predominantly affecting adolescents and young adults.
renal carcinoma (1 paper, 2020). A carcinoma arising from the epithelium of the renal parenchyma or the renal pelvis. "The relationships between the tumor expression of TIGAR and the clinicpathological profiles in renal cancer are investigated in our study for the first time." (PMID 31892967, 2020).
renal fibrosis (1 paper, 2022). A final common manifestation of a wide variety of chronic kidney diseases characterized by glomerulosclerosis and tubulointerstitial fibrosis. "Our previous study demonstrated that Sirtuin 3 deficiency that upregulated TIGAR in cardiomyocytes also sensitized Ang‐II‐induced renal fibrosis via promoting pericyte‐fibroblast transition, iron overload, and reactive oxygen species (ROS)." (PMID 35441828, 2022). "Our present study suggests that TIGAR is involved in Ang‐II‐induced renal fibrosis and glomerular injury, although it has little effect on blood pressure and renal function." (PMID 35441828, 2022). "Collectively, these results demonstrate that TIGAR is important in protecting the kidney from Ang‐II‐induced renal fibrosis and glomerular injury, although it has little effect on blood pressure and renal function." (PMID 35441828, 2022). "Knockout of TIGAR sensitizes Ang‐II‐induced renal fibrosis and injury." (PMID 35441828, 2022).
serous ovarian cancer (1 paper, 2019). "Importantly, TCGA data analysis indicates that higher expression of TIGAR is observed in many different cancer types, and patients with higher TIGAR expression show poor overall survival outcome in high-grade serous ovarian cancer." (PMID 31508509, 2019).
T-cell leukemia (1 paper, 2021). A malignant disease of the T-lymphocytes in the bone marrow, thymus, and/or blood. "Depletion of TIGAR expression by siRNA decreases the percentage of senescent cells in adult T-cell leukemia cells in response to low doses of Nutlin-3a." (PMID 34299056, 2021).
ulcerative colitis (1 paper, 2015). An inflammatory bowel disease involving the mucosal surface of the large intestine and rectum. "In highly proliferative tissues such as the intestine, a lack of TIGAR in vivo leads to decreased regeneration after acute stresses such as ulcerative colitis and irradiation, indicating an important role of TIGAR in proliferation." (PMID 25243985, 2015).
uterine carcinosarcoma (1 paper, 2022). A usually aggressive malignant neoplasm arising from the uterine corpus and less often the cervix. "According to cBioportal, the most common genetic alteration in TIGAR is amplification, but even in the tumor types in which the TIGAR DNA sequence is most altered, that is, uterine carcinosarcoma, genomic alterations are found in only 7% of the patients." (PMID 35163828, 2022).